CYP46A1 (cytochrome P450 family 46 subfamily A member 1)
Diseases named in the same sentence as CYP46A1 in open-access papers (continued):
Sharing a sentence is not in itself a finding about the gene and the disease.
epilepsy (2 papers, 2021 to 2026). A brain disorder characterized by episodes of abnormally increased neuronal discharge resulting in transient episodes of sensory or motor neurological dysfunction, or psychic dysfunction. "Inhibition of CYP46A1 is supposed to provide a novel treatment for disorders associated with neural hyperexcitation, such as epilepsy and epileptic syndromes." (PMID 41683437, 2026). "Conversely, CYP46A1 inhibition could be of therapeutic value in pathological conditions that promote excessive glutamatergic excitation such as those occurring in schizophrenia, epilepsy, and hyperalgesia." (PMID 34305573, 2021).
epileptic seizures (2 papers, 2024). "CYP46A1 inhibition was beneficial in mouse models and a subset of patients with certain seizure types, whereas CYP46A1 activation by EFV was required to reduce seizure frequency in a mouse model of epileptic seizures." (PMID 38396919, 2024).
schizophrenia (2 papers, 2021 to 2022). A major psychotic disorder characterized by abnormalities in the perception or expression of reality. "Inhibition of CYP46A1 has therapeutic relevance to CNS hyperexcitability supported the therapeutic way of lowering 24OHC to schizophrenia." (PMID 34408685, 2021).
tauopathies (2 papers, 2018 to 2023). "The data indicate that CYP46A1, by restoring 24-OHC levels in the brain, may be considered a potential therapeutic target for tauopathies, including AD." (PMID 36978879, 2023).
AIDS (1 paper, 2020). A syndrome resulting from the acquired deficiency of cellular immunity caused by the human immunodeficiency virus (HIV). "Moreover, restoration of the activity of the CYP46A1/24OHC signalling axis by EFV, a medication currently in widespread use for the treatment of AIDs, might be a promising GBM therapeutic strategy." (PMID 31777202, 2020).
atherosclerosis (1 paper, 2025). A disease characterized by the build-up of fatty material and calcium deposition in the arterial wall resulting in partial or complete occlusion of the arterial lumen.
Cerebellar atrophy (1 paper, 2022). Cerebellar atrophy is defined as a cerebellum with initially normal structures, in a posterior fossa with normal size, which displays enlarged fissures (interfolial spaces) in comparison to the foliae secondary to loss of tissue. "Intriguingly, in SCA2 and SCA3, CYP46A1 also becomes defective, and delivery of CYP46A1 to the cerebellum can prevent Purkinje cell loss and cerebellar atrophy." (PMID 35420383, 2022).
dementia (1 paper, 2025). Loss of intellectual abilities interfering with an individual's social and occupational functions. "The aim of this study was to assess the usefulness of ABCA1, ABCB7, ABCB1, APOE, CYP46A1, and LRP1 genotyping as promising dementia risk factors among a wide group of patients diagnosed first with hyperlipidemia." (PMID 41226793, 2025).
diabetes (1 paper, 2019). "Our data showed that this harmony between HMG-CoA reductase and CYP-46A1 is disrupted in diabetes; however, ginger extract can correct this disturbing effect." (PMID 31379996, 2019). "Although CYP46A1 protein level decreased in diabetes, its level is increased by ginger extract treatment; with 400 mg/kg of ginger extract, it reached to control group’s level, which could reduce the cholesterol accumulation and it has beneficial effects on cholesterol hemostasis in the brain." (PMID 31379996, 2019).
Iron deficiency anemia (1 paper, 2020). "The novel observation that iron depletion induces Cyp46a1 as the rate-limiting enzyme of cholesterol degradation provides a hint of why iron-deficiency anemia patients show lower blood cholesterol levels, and how iron influences steroidogenesis." (PMID 33023155, 2020).
liver cancer (1 paper, 2020). An epithelial or non-epithelial malignant neoplasm that arises from the liver. "At the cellular level, YBX3 and CH25H were highly expressed in liver cancer cell lines, and ABCA6, PLIN5, AMACR, AKR1D1, CYP27A1, CYP46A1 were highly expressed in liver cancer cell lines in CCLE." (PMID 32627826, 2020).
Machado-Joseph disease (1 paper, 2021). "In patients with HD as well as Machado-Joseph disease (MJD or Sca3), the levels of CYP46A1 were reduced in the affected brain regions, the striatum in HD and the cerebellum in MJD patients." (PMID 34305573, 2021).
Obesity (1 paper, 2021). Accumulation of substantial excess body fat. "Additionally, other causal genes are highly expressed or known to act in human brain function (i.e., NEGR1, GNPDA2, CYP46A1, DGKH) and various carcinomas (i.e., PMAIP1, HORMAD1, FES, BCAS3), indicating the potential role of metabolic dysregulation in the pathogenesis of obesity and cardiac events." (PMID 33910581, 2021).
pancreatic neuroendocrine tumor (1 paper, 2024). Pancreatic endocrine tumor, also known as pancreatic neuroendocrine tumor (PNET), describes a group of endocrine tumors originating in the pancreas that are usually indolent and benign, but may have the potential to be malignant. "Moreover, CYP46A1 transcripts are overexpressed in certain human pancreatic neuroendocrine tumor samples, correlating with tumor diameter." (PMID 38725627, 2024).
retinal degeneration (1 paper, 2016). Degeneration of the retina. "Amelioration of voriconazole-induced damage by 24(S)-HC supports the hypothesis that voriconazole induces retinal degeneration via inhibition of CYP46A1." (PMID 27653972, 2016). "Despite this, it is possible that 24(S)-HC synthesis is involved in glaucomatous retinal degeneration, and experimental IOP elevation in rats facilitates retinal cyp46a1 expression followed by sustained increases in 24(S)-HC28." (PMID 27653972, 2016).
synucleinopathy (1 paper, 2025). A neurodegenerative disease that is characterized by the abnormal accumulation of aggregates of alpha-synuclein protein in neurons, nerve fibers or glial cells. "Our results indicate that CYP46A1 promotes α-Syn pathology and nigrostriatal dopaminergic degeneration, whereas depletion of CYP46A1 attenuates damage in a mouse model of synucleinopathy." (PMID 39964974, 2025).
neurodegenerative disease (16 papers, 2016 to 2025). A disorder of the central nervous system characterized by gradual and progressive loss of neural tissue and neurologic function. "We suggest that CYP46A1 activation is a valuable pharmacological target for enhancing estrogen signaling in women at risk of developing neurodegenerative diseases." (PMID 38266095, 2024). "Altered CYP46A1 expression has been associated with several neurodegenerative diseases and changes in cognition." (PMID 27491694, 2016). "CYP46A1, crucial for brain cholesterol turnover and reduced in some neurodegenerative diseases, is a potential neuroprotective target." (PMID 40045480, 2025). "At these low doses, EFV effectively activates CYP46A1 in mice and has demonstrated significant efficacy across various animal models of neurodegenerative diseases." (PMID 40540390, 2025). "In these trials, low doses (50 and 200 mg daily for 20 weeks) of EFV were used to activate CYP46A1 in individuals with early-stage AD, suggesting its potential as a therapeutic approach for neurodegenerative diseases." (PMID 40540390, 2025). "Upregulation of CYP46A1 has been demonstrated to have beneficial effects for a number of neurodegenerative diseases, including AD, HD and PD." (PMID 36674804, 2023). "Collectively, the AAV-CYP46A1 delivery to animal models of AD, HD, Sca3, and ALS enabled major insights into the role of the CYP46A1 defect in neurodegenerative diseases and CYP46A1 mechanisms of therapeutic action." (PMID 34305573, 2021). "Decreases of CYP46A1 levels in patients with severe neurodegenerative diseases, like AD, HD, and Scas, and the phenotypic impairment observed in Cyp46a1–/– mice, prompted studies of potential detrimental consequences of CYP46A1 inhibition in adult mice." (PMID 34305573, 2021). "The EFV dosage used here (0.09 mg/kg/day) is 300–400-fold lower than that used for HIV patients, activates Cyp46A1 in mice and has been very effective in all animal models of neurodegenerative diseases." (PMID 33795005, 2021). "Our data also suggest that targeting CYP46A1 as a therapy for AD or other neurodegenerative diseases may lead to different outcomes in men and women, and this should be considered when designing therapeutic strategies." (PMID 38266095, 2024). "Moreover, AAV-based CYP46A1 overexpression, the enzyme involved in cholesterol pathway, has been demonstrated to be efficient in several neurodegenerative diseases." (PMID 38931878, 2024). "Thus, a number of brain disorders appeared to have changes in CYP46A1 activity, and these disorders were not only limited to neurodegenerative diseases." (PMID 34305573, 2021). "This review will first summarize the early seminal research, which created conceptual and pre-clinical bases for the on-going clinical pharmacological and gene therapy strategies developed to use CYP46A1 as a therapeutic target to treat neurodegenerative diseases." (PMID 34305573, 2021). "Interestingly, increasing the cerebral activity of CYP46A1 has been suggested to have therapeutic potential towards neurodegenerative disease." (PMID 31541728, 2019). "Interestingly, one of the few factors that influence the transcription of CYP46A1 is oxidative stress, perhaps as a defence mechanism against the progression of neurodegenerative disease." (PMID 30936243, 2019). "Because ALS is a neurodegenerative disease, we speculated that, when cholesterol is released by neurons as they die, it would be metabolized by CYP46A1 to 24S-hydroxycholesterol (24S-HC) and by CYP27A1 to members of the acidic pathway of bile acid biosynthesis (respectively)." (PMID 27811233, 2017).
tumor (8 papers, 2016 to 2025). "CYP39A1 and CYP46A1 were also significantly associated with tumour stage and lymph node stage." (PMID 27341022, 2016). "Among PNETs, TANs assist with neoangiogenesis and tumor growth through the simultaneous overexpression of the enzyme Cyp46a1 and regulation of hypoxia inducible factor 1-α (HIF 1-α)." (PMID 40565098, 2025). "While this was observed among SiNETs and PNETs through the observations of C3a upregulation and Cyp46a1 overexpression, respectively, there needs to be a validation of these targets to conclude their relationship with tumor growth." (PMID 40565098, 2025). "Overexpression of CYP46A1 or the use of activator suppressed cell proliferation and in vivo tumor growth by increasing 24OHC levels." (PMID 32802843, 2020). "Efavirenz, an anti‐HIV drug, crosses the BBB and shows anti‐tumor effect though activation of the CYP46A1/24OHC axis." (PMID 31777202, 2020). "Ectopic expression of CYP46A1 suppressed cell proliferation and in vivo tumour growth by increasing 24OHC levels." (PMID 31777202, 2020). "Single‐cell RNA‐seq data further demonstrated that CYP46A1 is mainly expressed in neurons, astrocytes and oligodendrocyte precursor cells (OPCs) and to a lesser extent in tumour cells." (PMID 31777202, 2020). "LN229 and GBM#P3‐lenti‐CYP46A1 or GBM#P3‐lenti‐control cells were injected intracranially into mice to evaluate tumour growth in vivo." (PMID 31777202, 2020). "An activator of CYP46A1 inhibited tumour growth in vitro and in vivo by increasing the production of the cholesterol metabolite 24OHC, thus disturbing cholesterol homeostasis in GBM." (PMID 31777202, 2020). "For both cell types, CYP46A1 overexpression inhibited tumour growth, as observed in haematoxylin and eosin (HE) staining, and prolonged overall survival in mice (P < 0.05)." (PMID 31777202, 2020). "CYP46A1 was highly expressed at the leading edge (which is mainly comprised of normal brain cells) compared with other tumour regions." (PMID 31777202, 2020). "Strong staining reflected a poorer outcome, with patients who had strongly staining tumours for CYP46A1 (n=173) surviving a mean of 87 months (95% CI 76-98)." (PMID 27341022, 2016). "Immunostaining for CYP46A1 showed 27.7% of primary tumours were strongly stained." (PMID 27341022, 2016). "Tumours demonstrating strong CYP46A1 immunostaining (n=173) had a mean patient survival of 87 months (95% CI 76-98) whereas negative/weak/moderate CYP46A1 immunostaining (n=452) was associated with a mean patient survival of 122 months (95% CI 112-131)." (PMID 27341022, 2016). "Cyp46a1 is overexpressed in some human pNET samples, and there is a linear correlation among Cyp46a1, VEGF and tumor diameter in G1 pNET patients." (PMID 36355141, 2022). "IHC data from the Human Protein Atlas (n = 17) corroborated these results, confirming high expression of CYP46A1 in normal brain (Fig EV2A), which decreased with increasing tumour grade (Fig EV2B and C)." (PMID 31777202, 2020). "CELF5 was low-expressed in tumor cell line; AMACR, CYP27A1, CYP46A1, and CH25H were high-expressed in tumor cell line in CCLE." (PMID 32117422, 2019). "CYP7B1, CYP8B1, CYP39A1, CYP46A1 and CYP51A1 each displayed a statistically significant relationship with location of tumour in the colon versus the rectum." (PMID 27341022, 2016). "Tumours that were negative for CYP46A1 (n=74) showed a mean patient survival of 117 months (95% CI 95-138), weakly stained tumours (n=173) had a mean survival of 128 months (95% CI 113-144) and moderately stained tumours (n=205) had a mean survival of 113 months (95% CI 100-126)." (PMID 27341022, 2016). "When the primary tumours of lymph node positive cases (Dukes C, stage 3) were compared to the paired lymph node metastasis, expression of CYP2R1, CYP8B1, CYP39A1, CYP46A1 and CYP51A1 were each significantly reduced in the lymph node metastasis." (PMID 27341022, 2016).
brain disorder (6 papers, 2016 to 2026). A disease affecting the brain or part of the brain. "How can CYP46A1 affect multiple brain processes and be associated with different brain diseases?" (PMID 34305573, 2021). "The potential therapeutic role of CYP46A1, demonstrated in numerous models of brain disorders, is currently being evaluated in early clinical trials." (PMID 34305573, 2021). "An explanation was provided for how one enzyme, CYP46A1, can affect multiple pathways and processes in the brain and serve as a common potential target for various brain disorders." (PMID 34305573, 2021). "On the other hand, the overexpression and pharmacological activation of Cyp46A1 induce beneficial effects and rescue brain disorders." (PMID 33795005, 2021). "We obtained additional support for the sterol flux hypothesis and expanded our understanding of how CYP46A1 can be a common therapeutic target for various brain disorders." (PMID 34235635, 2021). "CYP46A1 (cholesterol 24-hydroxylase, CH24H) is mainly responsible for the metabolism of cholesterol to 24(S)-hydroxycholesterol in the brain and is implicated in many brain disorders through the mediation of excitatory amino acid transporter 2 (EAAT2) and N-methyl-D-aspartate (NMDA) receptors." (PMID 41683437, 2026). "Then, the current clinical trials evaluating CYP46A1 modulations will be described, after which a discussion of the most recent studies aimed at understanding how this single enzyme, CYP46A1, can represent a common therapeutic target for various brain diseases." (PMID 34305573, 2021). "Thus, various brain diseases and apparently unlinked biological processes could be affected by CYP46A1 activity modulation, raising a question of how one enzyme, CYP46A1, can elicit all these multiple brain effects and become a potential therapeutic target for so many different brain disorders." (PMID 38719151, 2024). "In mouse models, pharmacologic CYP46A1 activation with low-dose efavirenz or by gene therapy mitigates the manifestations of various brain disorders, neurologic, and nonneurologic, by affecting numerous, apparently unlinked biological processes." (PMID 38719151, 2024).
cancer (3 papers, 2020 to 2021). A tumor composed of atypical neoplastic, often pleomorphic cells that invade other tissues. "By analysing the Cancer Genome Atlas (TCGA) pan‐cancer data including 31 different cancer types, the expression of CYP46A1 was found to be significantly increased in normal brain compared with GBM and LGG." (PMID 31777202, 2020). "Notably, exogenous cholesterol treatment or CYP46A1 knockdown partially restored growth inhibition of GBM cells induced by EFV, suggesting that the anti‐cancer effect of EFV is mediated at least partially, by regulating cholesterol levels." (PMID 31777202, 2020).
infection (3 papers, 2018 to 2023). The state of being infected such as from the introduction of a foreign agent such as serum, vaccine, antigenic substance or organism. "Indeed, we observed that the expression of CYP46A1, responsible for the production of 24(S)HC27, was also induced upon infection in an IL-36-dependent way." (PMID 29367626, 2018).
neurologic diseases (3 papers, 2021 to 2026). "The contribution of CYP46A1 to various neurological diseases and potential ways to regulate the activity of this enzyme is discussed in a recent review." (PMID 39403150, 2024). "More comprehensive reviews on CYP46A1, oxysterols, and the links between CYP46A1, cholesterol homeostasis in the brain, and neurological disorders can be found elsewhere." (PMID 34305573, 2021). "Thus, CYP46A1 being involved in the efflux of cholesterol from the brain as well as in the activation of cholesterol biosynthesis in this organ, turns out to be a crucial player in the manifestation of various neurological diseases such as Alzheimer’s disease." (PMID 39403150, 2024).
cardiovascular diseases (1 paper, 2023). "In addition, these compounds enhanced the neuronal expression of CYP46A1 with promising effects in different neurodegenerative and cardiovascular diseases." (PMID 36674804, 2023).
inflammation (1 paper, 2025). Aberrant reaction of the microcirculation characterized by movement of fluid and leukocytes from the blood into extravascular tissues. "Previous research has indicated that overexpression of CYP46A1 in the CP can enhance cognitive function and reduce brain inflammation in mice." (PMID 40645956, 2025).
CYP46A1 also shares sentences with these, for which no sentence is quoted: depression (5 papers); amyloid (4); amyotrophic lateral sclerosis (3); open-angle glaucoma (3); Dravet syndrome (2); scrapie (2); spinocerebellar ataxia (2); Atrophy (1); autism spectrum disorder (1); central nervous system disorder (1); Cerebral ischemia (1); cervical cancer (1); dyslipidemia (1); epileptic encephalopathies (1); epileptic syndromes (1); experimental autoimmune encephalomyelitis (1); hyperlipidemia (1); influenza (1); lymph node metastasis (1); multiple sclerosis (1); Parkinson's (1); protein misfolding diseases (1); Rett syndrome (1); sporadic CJD (1); Type 2 Diabetes (1); viral infection (1).